HK2 (hexokinase 2)
Diseases named in the same sentence as HK2 in open-access papers (continued):
Sharing a sentence is not in itself a finding about the gene and the disease.
cancer (continued). "The newly identified NTD regulatory site of HK2 is a promising target for the design of anticancer therapeutics that would reduce the rate of glycolysis in cancer through specific inhibition of the upregulated HK2." (PMID 33187984, 2021). "On the project, we predicted the expression differences of HK2 in cancers through bioinformatics investigation, and verified the HK2 expression in ESCA through in vitro experiments." (PMID 34708035, 2021). "Conversely, the levels of E-cadherin and CK-18 were induced, and those genes related to EMT induction and cancer aggressiveness were downregulated upon knockdown of HK2." (PMID 34174908, 2021). "FOXC2 can interact through a crossbridge to bind with YAP to both stimulate HK2 and enhance glycolysis in cancer cells." (PMID 34771718, 2021). "The results indicated that the expression of HK2 in cancer stage 2 was higher than that in cancer stage 3 (P < 0.05)." (PMID 34708035, 2021). "Among these enzymes, hexokinase 2 (HK2) stands out because of its elevated or induced expression in numerous cancers, including HCC9." (PMID 33594203, 2021). "HK1 generally exists in normal tissues, and HK2 is highly expressed and facilitates chemoresistance in various cancers." (PMID 34540667, 2021). "HK1 is ubiquitously expressed and is the main hexokinase expressed in most normal adult tissues, while HK2 is highly expressed in many cancers and constitutes the predominant hexokinase in only a limited number of adult tissues." (PMID 34378321, 2021). "The absence of association between 18F-FDG uptake ratio and degrees of GLUT1 and HK2 expression also was found within subgroups divided by primary cancer site." (PMID 34249674, 2021). "HK2, by physically and functionally interacting with the mitochondria, couples metabolic activity and cell proliferation in cancer cells." (PMID 33753739, 2021). "They interacted with transcription factor receptors, such as aryl hydrocarbon receptor, then promoted the transcriptional expression of glycolytic key enzymes, such as hexokinase 2 or pyruvate kinase M2, facilitated cancer cells progression." (PMID 35083240, 2021). "The upregulation of hexokinase-2 (HK2) in many cancers and its limited expression in normal tissues make it a particularly attractive target for the selective inhibition of cancer growth and the eradication of tumors with limited side effects." (PMID 33187984, 2021). "Whilst present at low levels in most normal adult cells, HK2 is highly expressed in embryonic tissues and cancer cells." (PMID 34100896, 2021). "HK2 is significantly overexpressed in various tumors, and its knockdown can suppress the aerobic glycolytic rate and proliferation of cancer cells." (PMID 34047477, 2021). "In the case of 3-BrPyr, the best characterized of these molecules, it perturbs the HK2-VDAC interaction on the mitochondrial surface of cancer cells and kill them by apoptosis or necrosis." (PMID 33946854, 2021). "The differences of HK2 expression in different cancer tissues were studied, and the mRNA and protein expression of HK2 in ESCA were verified by cell assay and immunohistochemistry (IHC)." (PMID 34708035, 2021). "Subtoxic levels of curcumin inhibited glucose uptake and glycolytic conversion to lactate in several cancer cell lines by decreasing the expression of key glycolytic enzymes like hexokinase 2 (HK2) and pyruvate kinase isoform M2 (PKM2)." (PMID 34201298, 2021). "Among the five HK isoforms, HK2 is highly expressed and functions as the predominant form in cancer cells." (PMID 34367462, 2021). "The interactive relationship between the PI3K/Akt signaling pathway and HK2 has also been confirmed in various cancers." (PMID 34758823, 2021). "Our gain-of-function and loss-of-function assays have uncovered the promoting role of HK2 in maintaining cancer stem cell-like ability and the acquisition of CDDP resistance." (PMID 34858863, 2021).
cancer (continued). "The HK family includes four isoforms (HK1–HK4), but HK2 is the only one overexpressed in several cancers." (PMID 33804240, 2021). "Numerous studies have reported that aberrant HK2 overexpression stimulates cancer development, metastasis, and therapeutic resistance to chemotherapy and radiation." (PMID 34174908, 2021). "The antifungal azole derivatives ketoconazole and posaconazole have shown some efficacy in targeting HK2 and inducing apoptosis in cancer cell models, and one phase 0 and two early phase 1 clinical trials are starting in glioma patients." (PMID 33946854, 2021). "Inhibition of HK2 has been shown to inhibit the proliferation of cancer cells by shifting the glycolytic pathway with reduced lactate formation." (PMID 33628847, 2021). "Specifically, it has been reported that STAT3 regulates the glucose metabolism through increasing the HK2 expression in cancer cells." (PMID 34326684, 2021). "Recently, our group identified that taurine upregulated gene 1 (TUG1) promotes cancer cell glycolysis and metastasis through the regulation of HK2." (PMID 33498721, 2021). "Molecularly Signal Transducer and Activator Of Transcription 3 (STAT3)-phosphorylation and hexokinase 2-expression were reduced in human cancer cells treated with CM from IL-17RB OE PSCs." (PMID 34771503, 2021). "The challenge lies in the development of HK2 inhibitors that target cancer but induce limited interference with the ubiquitously expressed HK1 isozyme." (PMID 33187984, 2021). "Of the four isoforms, HK1 is the most widely expressed and HK2 is present in cancer cells and PRs, which coincides with their predilection for aerobic glycolysis." (PMID 33627778, 2021). "Accumulating evidence has shown that elevated levels of HK2 lead to various malignant behaviors of cancer cells." (PMID 33718248, 2021). "The metabolic reactions of aerobic glycolysis are catalyzed by enzymes such as HK2, LDHB, and PKM2, which are implicated in cancer." (PMID 33849427, 2021). "Although HK2 was considered as a target against cancer, it is ambiguous how HK2 is targeted in MTB infection." (PMID 34068051, 2021). "Hexokinase 2 (HK2) can resist cancer cell apoptosis by expressing on mitochondria and binding to voltage-dependent anion channel 1 (VDAC1)." (PMID 33802591, 2021). "According to previous studies, HK2 is related to the pathogenesis of cancer and alterations in CpG methylation regulate HK2 expression level." (PMID 34041244, 2021). "Among all four isoforms of HK (HK1, HK2, HK3, and HK4), HK2 was found to be highly expressed in patients with carcinomas and considered the most efficient isoform in aerobic glycolysis." (PMID 34368116, 2021). "HK2 is one of the rate-limiting enzymes in the glycolysis pathway and has been recognized to regulate the malignant phenotype of cancer cells (i.e., cellular apoptosis and migration capabilities)." (PMID 33308298, 2020). "HK-2 was found to be overexpressed more than HK-1 in several cancer types compared with their normal counterpart." (PMID 32372141, 2020). "In consistent with former findings in other cancer tissues, HK2, both in mRNA and protein level, is highly expressed in tested HNSCC cell lines compared to normal human oral keratinocytes (NHOKs)." (PMID 32195170, 2020). "GPC1-subtype tumors displayed distinct Warburg-like proteomic features, with increased LDHA, PKM2, and HK2 expression that facilitates lactate production and confers resistance to hypoxic stress in cancer cells." (PMID 32620753, 2020). "Previous studies have demonstrated that HK2 activity is remarkably increased in various malignant neoplasms, as well as in CRC." (PMID 32245489, 2020). "A preclinical study has demonstrated that high uptake of 18F-FDG was correlated with increased Glut-1 and HK-2 expression in human cancers." (PMID 32811569, 2020). "HK2 expression is limited in most normal tissues but is frequently upregulated in various human cancers." (PMID 33324557, 2020).
cancer (continued). "Repressing glucokinase and expressing HK2 isoform by cancer cells allows the high glycolytic rates that occur in anaerobic metabolism in cancer development." (PMID 33182674, 2020). "The base model (DRE, PSA, and age) versus the full model (age, PSA, freePSA, and hk2) showed an AUC of 0.585 versus 0.711 for diagnosing any cancer, and AUC 0.709 vs. 0.798 in detecting high-grade cancer." (PMID 33050493, 2020). "Although numerous studies have shown the critical roles of cyclin A1 and p27 in regulating cell cycle progress in various cancer, however, the likely molecular regulation mechanism by which HK2 mediated cyclin A1 and p27 expression is less known." (PMID 33324557, 2020). "A strong correlation between CD68+ macrophages and the expression of GLUT1 and HK2 in cancer cells was found in patients with non-small-cell lung carcinoma (NSCLC)." (PMID 32486098, 2020). "We show here that, as in other cancer cells, HK2 is located mostly at the outer mitochondrial membrane, consistent with a role in energy modulation in MM cells." (PMID 32709889, 2020). "HK2 catalyzes the first committed step of glucose metabolism and is critically important for aerobic glycolysis in multiple cancer types." (PMID 33520999, 2020). "The obtained results showed that the down-regulation in the glycolytic metabolism, mainly in HK2 is in agreement with previous cancer metabolism reports." (PMID 33425736, 2020). "Since hexokinase serves as the gateway through which glucose enters the alternative metabolic pathway, HK-1 is redundant to the primary catalytic role of HK-2 to ensure the cancer cell a constant glycolytic flux." (PMID 32372141, 2020). "HK2 is widely over-expressed in cancer cells and plays a key role in aerobic glycolysis and anti-apoptosis capacity of tumor cells." (PMID 33143000, 2020). "In this study, it was revealed that capsaicin downregulates the hexokinase-2 expression and inhibits cancer cells glycolysis." (PMID 33379302, 2020). "It is found that HK2 is expressed in many types of cancers to promotes its growth through an increased glycolytic flux." (PMID 32874134, 2020). "Hexokinase II (HK2) is dominant isoform of HK in cancer cells, which plays important roles in cell survival and glycolysis." (PMID 33143000, 2020). "HK2 was well documented to play an essential part in the Warburg effect and to be a metabolic target in cancer treatment." (PMID 32279420, 2020). "Inhibition of HK2 has shown to inhibit proliferation and change the metabolic profile of cancer by shifting from glycolytic to OXPHOS pathway with reduced lactate formation." (PMID 32806533, 2020). "Administration of HK2 inhibitor, 2-DG, can induce cancer cell death by abrogating intracellular glycolysis." (PMID 31918722, 2020). "Recent research has highlighted that some lncRNAs are involved in the reactivation of HK2 inhibited by miRNAs in human cancers." (PMID 32885590, 2020). "In epithelial ovarian cancer, FOXM1 promotes reprogramming of glucose metabolism in cancer cells via activation of HK-2 and GLUT1 transcription." (PMID 32489324, 2020). "The anti-cancer properties of AT-I can be attributed to apoptosis and suppression of glycolysis, which, in turn, are mediated via AT-I-induced downregulation of HK2." (PMID 32273843, 2020). "Alterations of the essential enzymes PKM2 and HK2 participate in the Warburg phenotype of cancer cells." (PMID 32843908, 2020). "It was well documented that the mitochondrial translocation of HK2 promotes glucose phosphorylation and leads to lactate formation, which promotes cancer cell proliferation." (PMID 32279420, 2020). "Among them, HK2 is mainly expressed in cancers, and phosphorylates glucose to produce glucose-6-phosphate, a rate-limiting and irreversible step of glycolysis." (PMID 32042322, 2020). "Studies report the role of HIF-1α in HK2 expression, e.g., inhibition of HK2 resensitizes tamoxifen-resistant cells and HIF-1α, a transcription factor associated with hypoxia, is linked to cancer initiation." (PMID 32806533, 2020).
cancer (continued). "Consistent with these previous findings, our current data verified that HK2 promoted glycolysis and facilitated the proliferation, invasion, and cancer stem cell-like properties of PC cells." (PMID 33520999, 2020). "Since HK2 is an vital regulator of glycolysis, which has been previously reported to promote cancer progression, we suggested that HK2‐driven glycolysis was also involved during the process of the chemoresistance of GBM." (PMID 32279420, 2020). "The increase in mitochondrial‐bound HK2 exhibited cancer‐promoting effects by inducing glycolysis and the inhibition against apoptosis." (PMID 32279420, 2020). "With respect to metabolic regulation, VDAC also acts as platform for the anchoring of hexokinase 2 (HK2), the embryonic version of the first enzyme of glycolysis, to the OMM to facilitate the use of ATP by HK2 in cancer cells." (PMID 32548570, 2020). "For example, 2-Deoxy-Glucose (2DG), which binds and inhibits HK2, decreases glycolysis, and eventually induces ROS-mediated apoptosis in multiple cancer types (e.g., prostate cancer)." (PMID 33081387, 2020). "HK1 is widely expressed in adult tissues and is considered the housekeeping isoform of hexokinase, and HK2 is highly expressed in many cancer cells." (PMID 33275593, 2020). "EZH2 regulated aerobic glycolysis through miR-181b/hexokinase 2 (HK2) axis and played a positive role in cancer development." (PMID 32723346, 2020). "Mitochondrial HK2 exhibited cancer‐promoting effects by inducing glycolysis and the inhibition against apoptosis, which make it as an attractive drug target for human cancers." (PMID 32279420, 2020). "HK2 is one of the key enzymes of glycolysis, participating in the regulation of cancer cell metabolism and death, and its overexpression is significantly positively correlated with CRC recurrence." (PMID 32000836, 2020). "GLUT3 induction also correlates with the over-expression of glycolytic enzymes including HK2 and pyruvate kinase M2 (PKM2), which are associated with cancer invasiveness, metastasis, and poor prognosis." (PMID 32252351, 2020). "The observed shift in hexokinase (HK) isoforms, upregulation of HK2 in cancer cells, indicates a closer integration of mitochondria with glycolytic phosphotransfer." (PMID 32509571, 2020). "HOTAIR has been shown to enhance cancer cell energy metabolism in this kind of cancer through increasing HK2 expression." (PMID 33123468, 2020). "For instance, there is experimental evidence that miRNA-143 down-regulates Hexokinase 2 (HK2) which promotes cancer progression and the reduction in glucose metabolism." (PMID 33425736, 2020). "Our results also suggested that HK2 is essential for xanthohumol correlated metabolic changes and cancer cell apoptosis induction." (PMID 31595166, 2019). "Increased mitochondrial-bound HK2 exerts dual cancer-promoting effects by concomitantly promoting glycolysis and inhibiting apoptosis." (PMID 31201299, 2019). "As the first rate-limiting enzyme of glycolysis, HK2 is expressed at high level in human cancer cells." (PMID 31595166, 2019). "2-DG, a well-known HK2 inhibitor, induces cancer cell death by depleting intracellular glucose levels." (PMID 30952834, 2019). "Overexpression of HK2 has been found in many cancer cells, and forms the basis for 18FDG-PET imaging, a common clinical technique used to detect tumors." (PMID 31212816, 2019). "HK2, which is overexpressed in numbers of human cancer, is the rate-limiting enzyme catalyzes the first irreversible step of glycolysis." (PMID 31137633, 2019). "Lonidamine, a pharmacological inhibitor of HK2, can effectively suppress multifarious cancer cell proliferation and metastasis in vitro, in vivo, as well as clinical trials, which is thus used in our experiment." (PMID 31607919, 2019). "HectH9 deficiency mitigates the HK2-VDAC association at the mitochondria, thereby inducing apoptosis along with glycolysis suppression in cancer cells." (PMID 31201299, 2019).
cancer (continued). "Subsequently, we investigated an association between the rs17723799 genotype and phenotype by measuring target gene Hexokinase 2 (HKII) expression in cancer cell lines and controls." (PMID 30818878, 2019). "Induction of HK2 was further validated by western blot analysis in different cancer cell lines, SW480 and HCT116." (PMID 31040906, 2019). "The ubiquitination-defective mutant (K21/K104R) of HK2 had impaired mitochondrial transport and a diffused appearance in the cytosol in various cancer cell lines." (PMID 31201299, 2019). "The induced lactate production resulting from HK2 overexpression was attenuated upon HectH9 deficiency, establishing a functional link between HectH9 and HK2 in promoting cancer glycolysis." (PMID 31201299, 2019). "Although the anticancer properties of QUE are well known, the relationship between QUE and cancer metabolism is poorly understood, including the role of key metabolic enzymes such as HK2." (PMID 31137633, 2019). "In summary, our study demonstrates that PD synergised with 2‐DG to enhance its anti‐cancer efficacy by inhibiting the ROS/PI3K/AKT/HIF‐1α/HK2 signalling axis, providing a potential anti‐cancer strategy." (PMID 30920152, 2019). "Mitochondria-localized HK2 has been shown to be required for escaping from mitochondrial cell death in several types of human cancer 28-31." (PMID 31595166, 2019). "WT and the K21/K104R mutant of HK2 were restored in the cancer cells infected with viruses containing a shRNA targeting the 3’-UTR of HK2." (PMID 31201299, 2019). "The simultaneous co-inhibition of LDHA and HK2 can induce the death of cancer cells that depend upon glycolysis." (PMID 31483850, 2019). "It has been reported that HK2 is exclusively upregulated in many types of cancers and plays a key role in the Warburg effect." (PMID 31655629, 2019). "In order to further determine the mechanism of QUE modulation of HK2 expression level, we focused on the Akt-mTOR pathway, which regulates a wide variety of cellular processes including cancer cells glucose metabolism." (PMID 31137633, 2019). "Our finding of statistically higher HK2 immunoreactivity in metastatic foci compared to their corresponding primary carcinomas prompted us to investigate the effect of HK2 on cell migration and invasion." (PMID 31212816, 2019). "This hormone-DNA circuit increases hK2 expression which establishes a feed-forward process leading the cancer to bind more [225Ac]hu11B6." (PMID 29691406, 2018). "Usually, HK2 is regarded as a principle enzyme in cancer metabolism; however, our study suggests that HK1 is the main enzyme converting glucose to glucose-6-phosphate in SPNs." (PMID 29552289, 2018). "HK2 becomes overexpressed in many cancer types, either in conjunction or instead of the normal HK1 isozyme, where it binds to the outer mitochondrial membrane via the VDAC1 channel." (PMID 30400835, 2018). "Given its restricted distribution pattern in normal adult tissues and selective overexpression in cancer cells, HK2 has the potential to be a promising candidate for anticancer therapy." (PMID 29696133, 2018). "Not coincidentally, VDAC1-HKs complexes are exploited in tumors, since mitochondrial HK2 increases the glycolysis rate, participating to the “Warburg effect,” and protects cancer cells from apoptosis." (PMID 29682501, 2018). "By upregulating transcription of HIF-1α target genes, cancer cells increase the levels and activity of glycolytic enzymes, like hexokinase 2 (HK2) and glucose transporters (GLUT1 and GLUT3)." (PMID 29342092, 2018). "MYC is known to promote glycolysis in cancer cells through induction of glucose transporters and the glycolytic enzymes hexokinase 2 and lactate dehydrogenase A28." (PMID 30154400, 2018). "First, targeting and binding hK2, an epitope expressed exclusively on prostate tissue and cancer in vivo; second, internalizing and transporting radionuclide cargo inside the cell to optimize the geometry of parent and progeny alpha decay." (PMID 29691406, 2018).